IFNG (interferon gamma)
Diseases named in the same sentence as IFNG in open-access papers (continued):
Sharing a sentence is not in itself a finding about the gene and the disease.
severe combined immunodeficiency (11 papers, 2010 to 2025). Severe combined immunodeficiency (SCID) comprises a group of rare monogenic primary immunodeficiency disorders characterized by a lack of functional peripheral T lymphocytes resulting in early-onset severe respiratory infections and failure to thrive. "However, splenic cells from mice with severe combined immunodeficiency (SCID) that lack T cells produce elevated levels of IFNγ after stimulation with S. Typhimurium, suggesting that NK or other innate cells are responsible for IFNγ production." (PMID 21048923, 2010).
Acute hepatitis (10 papers, 2010 to 2024). Acute hepatic injury resulting from inflammation typically accompanied by increased serum alanine transaminase activity. "We report the case of a patient with adult-onset immunodeficiency with anti-interferon gamma antibodies who presented with acute hepatitis ultimately diagnosed with MAS through liver biopsy." (PMID 38178160, 2024). "As plant lectin concanavalin A (ConA) is another widely used mouse model for introducing immune-mediated acute hepatitis by inducing TNFα, IL-6 and IFNγ, we further detected the role of Bcl-3 in ConA-induced liver injury." (PMID 34853447, 2022).
amyloid (10 papers, 2006 to 2024). "Thus, higher induction of IFNG in old female microglia likely drives them more quickly towards senescence and subsequently results in higher susceptibility to AD pathology (i.e., amyloid)." (PMID 36945656, 2023). "Lower production of IFNγ by high responders' cells seems also to fit well with the notion of the role of this cytokine in stimulating the clearing of Aβ deposits; thus, high responders would be at higher risk of amyloid plaque accumulation and, possibly, faster progression of the disease." (PMID 22428008, 2012). "Since we found a significant induction of IFITM3 in response to various inflammatory stressors (LPS, TNFα, and IFNγ) and recent findings suggest a novel role of IFITM3 in amyloid pathology, we sought to examine whether amyloid peptide could induce IFITM3 expression in primary microglia." (PMID 36012150, 2022).
ankylosing spondylitis (10 papers, 2015 to 2024). An autoimmune chronic inflammatory disorder characterized by inflammation in the vertebral joints of the spine and sacroiliac joints. "The case‐control study was designed to investigate the genetic effects of interferon‐gamma (IFN‐γ) rs2069727 and rs1861494 polymorphisms on ankylosing spondylitis (AS) susceptibility in a Chinese Han population." (PMID 32729668, 2020).
Babesia infection (10 papers, 2017 to 2025). "Activation of acquired immune responses during Babesia infection leads to the production of IFNγ, mainly by CD4+ T lymphocytes, which activates additional myeloid and lymphoid immune cells." (PMID 35062784, 2022). "It has also been shown that natural killer (NK) cells are a potential source of IFNγ early during acute Babesia infection, which may play a role in fine-tuning the profile of cytokine expression and boost activation of monocytes, macrophages, and DC." (PMID 35062784, 2022).
Blau syndrome (10 papers, 2021 to 2026). Blau syndrome (BS) is a rare systemic inflammatory disease characterized by early onset granulomatous arthritis, uveitis and skin rash. "In the iPS-ML cells from 201B7E1, we previously confirmed that NOD2 expression was induced by IFNγ using macrophages induced by further differentiation, similar to observations obtained with iPS-ML cells generated from Blau syndrome patient-derived iPS cells." (PMID 37415984, 2023). "Along with the induction of NOD2 expression by IFNγ treatment, TNFA expression was induced not only in cells with the p.R334W mutation associated with Blau syndrome, but also in WT cells." (PMID 37415984, 2023). "This study demonstrated that abnormal cytokine expression in macrophages from untreated patients requires IFNγ stimulation, and that anti-TNF treatment corrects the abnormalities associated with Blau syndrome, even in the presence of IFNγ." (PMID 35711422, 2022). "This was established through iPS cells from patients with Blau syndrome that were differentiated into macrophages and confirmed that IFNγ treatment enhanced the expression of NOD2." (PMID 35711422, 2022). "Although the expression of both TNFα and IFNγ in the lesional skin of a Blau syndrome patient was previously reported, the genetic background of the patient was not clarified." (PMID 33923123, 2021). "Therefore, although the molecular mechanisms by which the genetic mutations in NOD2 lead to granuloma formation remain unclear, it is possible that prior exposure to TNFα combined with IFNγ stimulation may provide the impetus for the clinical manifestations of Blau syndrome." (PMID 35711422, 2022). "qPCR experiments in both iPS-ML cell lines showed that stimulation with IFNγ for 2 h induced NOD2, regardless of the presence or absence of the Blau syndrome-associated mutation." (PMID 37415984, 2023). "Macrophages, differentiated from the peripheral blood of Blau syndrome who did not receive anti-TNF treatment, released inflammatory cytokines after being primed with IFNγ." (PMID 35711422, 2022).
cholangiocarcinoma (10 papers, 2010 to 2025). A carcinoma that arises from the intrahepatic biliary tree (intrahepatic cholangiocarcinoma) or from the junction, or adjacent to the junction, of the right and left hepatic ducts (hilar cholangiocarcinoma). "In addition, IL2, IL8, and interferon-gamma were found to be increased in EVs isolated from patients with cholangiocarcinoma compared with healthy controls." (PMID 37298585, 2023).
diabetic retinopathy (10 papers, 2011 to 2025). "Evidence from our study indicates that IFNγ may also be important in mouse models of diabetic retinopathy." (PMID 37670018, 2023). "The mechanisms by which IFNγ supports the development of diabetic retinopathy have not been investigated." (PMID 37670018, 2023).
Ewing sarcoma (10 papers, 2012 to 2025). A small round cell tumor that lacks morphologic, immunohistochemical, and electron microscopic evidence of neuroectodermal differentiation. "HLA class I and APP loss in Ewing sarcoma cell lines is reversible using IFNγ." (PMID 38318504, 2023). "Of note, HLA-G expression is induced by IFNγ in Ewing sarcoma cell lines, and is detected in a majority of tumor biopsies on both tumor and infiltrating myeloid cells." (PMID 38318504, 2023). "Furthermore, USP6-expressing Ewing sarcoma and NK cells participate in a paracrine immunostimulatory feedforward loop, wherein IFNγ secreted by activated NK cells feeds back on USP6/Ewing sarcoma cells to induce synergistic expression of chemokines CXCL9 and CXCL10." (PMID 37615015, 2023). "Both IFNγ and IRF3 were predicted to be upstream regulators of the overlapping gene signatures induced by radiotherapy in Ewing sarcoma." (PMID 40858520, 2025). "One study referred to an enrichment of anti-tumor immune regulatory mechanisms, including interferon-gamma (IFN-γ) and interferon-alpha (IFN-α) responses in Ewing sarcoma." (PMID 40007535, 2025). "Upon activation, NK cells secrete IFNγ, which feeds back on USP6-expressing Ewing sarcoma cells to synergistically induce CXCL9/CXCL10." (PMID 37615015, 2023). "To further illustrate the regulation of IFNγ signaling by SHP2 blockade in vivo, we utilized adoptive transfer of human bone Ewing’s sarcoma cells RD-ES and human PBMCs in NSG mice." (PMID 33446805, 2021). "Furthermore, USP6 renders Ewing sarcoma cells hyperresponsive to IFNs, such that IFN response genes are synergistically induced by ectopic IFNγ in Ewing sarcoma cells expressing USP6." (PMID 37615015, 2023).
extrapulmonary tuberculosis (10 papers, 2009 to 2026). A tuberculosis that occurs at body sites other than the lung. "We have recently reported that the ratio of these two key cytokines (IFNγ/IL10) shows significant correlation with clinical severity in extra-pulmonary tuberculosis,with higher IFNγ/IL10 ratio relating to less severe disease." (PMID 19274101, 2009). "Although the Interferon Gamma Release Assays (IGRA) is often used to identify latent tuberculosis, it also plays a crucial role in diagnosing active extrapulmonary tuberculosis." (PMID 35771875, 2022).
gestational diabetes (10 papers, 2016 to 2025). Carbohydrate intolerance first diagnosed during pregnancy. "EVs isolated from the plasma of women with gestational diabetes induce the release of pro-inflammatory cytokines including granulocyte-macrophage colony-stimulating factor (GM-CSF), interleukin (IL)-4, IL-6, IL-8, interferon-gamma (IFN-γ), and tumor necrosis factor-alpha (TNF-α)." (PMID 36982732, 2023).
histoplasmosis (10 papers, 2013 to 2023). A disease caused by the fungus Histoplasma capsulatum. "Immunity to histoplasmosis was perforin-dependent and perforin-independent, which included cytokine-mediated (IFNγ or TNα) mechanisms." (PMID 36177012, 2022).
Lymphadenopathy (10 papers, 2015 to 2023). Enlargement (swelling) of a lymph node. "FVB/Fas-/- lupus-like mice inhibited lymphadenopathy, splenomegaly, upregulated number of Treg cells, and IFNγ expression." (PMID 38164134, 2023).
Myalgia (10 papers, 2012 to 2023). "Polymyalgia rheumatica patients were shown to have a higher percentage of IL-2 and IFNγ producing CD4+ T cells in response to VZV stimulation using flow cytometry." (PMID 29118757, 2017). "Symptoms of arthralgia, myalgia, and fatigue occurring at the time of sampling were significantly associated with a higher proportion of CD8+ IFNγ and CD4+ interleukin (IL) 2–secreting cells, while headache was associated with higher CD4+ IL2 and IFNγ ELISpot response." (PMID 31784751, 2020). "Interestingly, arthralgia, myalgia and fatigue occurring at the time of study were associated with a higher proportion of CD8+ IFNγ and CD4+ IL-2-secreting cells, while headache was associated with higher CD4+ IL-2 and IFNγ ELISpot responses." (PMID 33679690, 2020). "Headache, fatigue, myalgia, and arthralgia were associated with the magnitude of T-cell response to pooled GP peptides, with higher CD4+ production of IL2 and CD8+ production of IFNγ, but not with antibody responses." (PMID 31784751, 2020).
oral lichen planus (10 papers, 2010 to 2025). Oral lichen planus is a chronic inflammatory oral condition of unknown aetiology characterized by T-cell-mediated chronic immune response and abnormal epithelial keratinization cycle. "Background and Objectives: Interferon-gamma (IFN-γ)/interleukin-4 (IL-4) ratio may indicate a change in the immune response with a potential pathological effect presented in oral lichen planus (OLP) patients." (PMID 31181785, 2019).
prediabetes (10 papers, 2019 to 2025). "In addition, the latest longitudinal study found that elevated plasma levels of IL-1β and IFNγ at baseline were significant predictors of the development of new-onset prediabetes after acute pancreatitis (NOPAP) during follow-up." (PMID 35498402, 2022).
pulmonary sarcoidosis (10 papers, 2005 to 2025). Sarcoidosis affecting the lung parenchyma. "To stay consistent with previous reports in pulmonary sarcoidosis, in which the majority of cells produced IFNγ but not IL17, we will refer to them as Th17.1 cells." (PMID 36720972, 2023). "Furthermore, the differential transcriptome features in PBMCs from patients with pulmonary sarcoidosis between patients with and without EPL were demonstrated, particularly the upregulations of IFNG and IFNLR1." (PMID 41463010, 2025).
rectal cancer (10 papers, 2011 to 2025). A primary or metastatic malignant neoplasm that affects the rectum. "Genetic variation of IFNG leads to an increased risk of colon and rectal cancer and affects its diagnosis and survival." (PMID 35265525, 2022). "A previous study examined genetic variation in IFNG, IFNGR1, IFNGR2 and IRF1-9 with the risk and survival of colon and rectal cancer." (PMID 25350395, 2014). "Gene expression levels of GZMA, GZMB, PRF1, IFNG and chemokine CXCL10 were compared between responsive versus non-responsive rectal cancer patients." (PMID 35534879, 2022).
rosacea (10 papers, 2020 to 2026). A chronic erythematous skin disorder that affects the face. "In rosacea, significantly higher expression levels of the Th1-signature cytokines, IFNγ, and tumor necrosis factor-α, also showed Th1 polarization." (PMID 36091020, 2022). "According to our epidermal RNA-seq data, the upregulated genes were mainly related to the IFNγ signaling pathway for rosacea lesions." (PMID 34290700, 2021). "Moreover, studies demonstrated the potential relationship between MLT target genes (MMP9, CCND1, EGFR, ICAM1, PTGS2, and SERPINE1) and rosacea-related key genes (IL-6, IL-1β, IFNγ, IL-17, and TNF-α)." (PMID 34899707, 2021). "Taken together, we suggest that IFNγ/STAT1 is the core of the critical gene regulatory network connecting the epithelial–immune crosstalk in rosacea development, and targeting IFNγ/STAT1 might be a potential therapy for the treatment of rosacea." (PMID 34290700, 2021). "IRF1 regulated the IFNγ/STAT1 signaling pathway in keratinocytes and enhanced their interaction with macrophages, which drove the persistent inflammatory response of rosacea and then induced clinical manifestations such as pustules, papules, and heat pain." (PMID 40635520, 2025). "Adaptive T cell–derived cytokines IFNG, IL17A, IL17F, and IL22 were significantly overexpressed in lesional rosacea skin, while IL4 was either undetectable or not increased." (PMID 36633910, 2023).
small cell lung carcinoma (10 papers, 2015 to 2025). Small cell lung cancer (SCLC) is a highly aggressive malignant neoplasm, accounting for 10-15% of lung cancer cases, characterized byrapid growth, and early metastasis. "Secondly, in addition to suppressing cell proliferation, CDK7 inhibition by YLK-5-124 was found to induce interferon gamma signalling along with other inflammatory response pathways in models of small cell lung cancer." (PMID 37076563, 2023).
thrombosis (10 papers, 2018 to 2025). "IFNγ levels obtained at hospital admission appear to inversely correlate with disease severity and predict the risk of complications such as ICU access, deep vein thrombosis, secondary bacterial infections, organ failure and death." (PMID 36016305, 2022).
tuberculous meningitis (10 papers, 2008 to 2023). "In this study, we evaluated and compared the accuracy of blood and cerebrospinal fluid (CSF) interferon release tests [interferon-gamma release assays (IGRAs)] in the diagnosis of tuberculous meningitis (TBM) by a meta-analysis of the relevant literature." (PMID 35531329, 2022).
vivax malaria (10 papers, 2012 to 2023). "The aim of this study was to evaluate whether polymorphisms in the TNFA, IFNG and IL10 genes would alter the levels of anti-PvAMA1, PvDBP and -PvMSP-119 IgG antibodies in patients with vivax malaria." (PMID 27435973, 2016). "However, this was the first Brazilian study to examine this set of SNPs (IFNG-183G > T, +874A > T; TNFA −238G > A, −308G > A and −1031T > C; IL10-592C > A, −819C > T) in control cases of vivax malaria." (PMID 27435973, 2016).
age-related macular degeneration (9 papers, 2011 to 2025). Age-related loss of vision in the central portion of the retina (macula), secondary to retinal degeneration. "Additionally, aqueous humor IFNγ levels also increased in patients with either aged cataract or age-related macular degeneration, indicating the involvement of Th cells in the pathogenesis of these two diseases." (PMID 38375484, 2024). "Immunization with an age-related macular degeneration (AMD)-specific epitope, carboxyethylpyrrole (CEP), resulted in the production of interferon-gamma (IFN-γ) and interleukin-17 (IL-17)-producing T cells, which then promoted macrophage polarization leading to CNV." (PMID 27532664, 2016).
airway allergy (9 papers, 2012 to 2025). "The inhibition of respiratory allergy was IFNγ-dependent indicating that immune responses to proteins of M. tuberculosis inhibited Derp1-induced allergic responses by a bystander mechanism." (PMID 32391011, 2020).
alcohol (9 papers, 2012 to 2025). "In a murine model of alcohol dependence, IFNG signaling is increased, though the mechanism for this is unknown." (PMID 37361874, 2023). "Four genes, MAPK1 (marijuana dependence in black women), MANBA (alcohol dependence in white men), HAAO (cocaine dependence in white women), and IFNG (opiates dependence in white women), met the threshold by the gene-based method only." (PMID 23365539, 2012).
aortic aneurysm (9 papers, 2013 to 2025). A ruptured aneurysm located in the wall of the proximal portion of the descending aorta proceeding from the arch of the aorta. "Similarly, the pro-inflammatory Interferon gamma (IFN-γ), active in aortic aneurysm, and arteriosclerotic plaque rupture, were demonstrated to reduce LOX mRNA and activity in rat aortic smooth muscle cells, partly via transcriptional downregulation, and also by reducing the LOX mRNA half-life." (PMID 32708046, 2020).
bacterial meningitis (9 papers, 2013 to 2024). Inflammation of the membranes surrounding the brain and spinal cord due to a bacterial infection. "This is in contradiction to recent experimental results describing IFNγ as an important contributor to the pathogenesis of bacterial meningitis." (PMID 27009189, 2016). "A systematic review of cytokine levels in lumbar CSF in TBM found that IFNγ, IL-13, and sIL-2R were increased in TBM compared with other causes of bacterial meningitis, whereas TNF, IL-1β, IL-1Ra, IL-8, IFNγ, sIL-2R, IL-13, and IL-17 were increased compared to viral or aseptic meningitis." (PMID 38264653, 2023). "In bacterial meningitis, the majority (23/36) of examined cytokines displayed elevated values with CCL7, TNF-α, CXCL1, and IFNγ showing consistent results with the literature (; Pinto)." (PMID 31727097, 2019).
campylobacteriosis (9 papers, 2014 to 2025). Infections with bacteria of the genus campylobacter. "Multiparameter flow cytometry was used to investigate T lymphocytes as a source of cytokines, including IFNγ, and to identify cytokine patterns associated with either campylobacteriosis or protection from disease." (PMID 25397604, 2014). "Analysis from a previously performed human challenge and re-challenge model using C. jejuni strain 81-176 showed association between pre-infection levels of IFNγ and protection from clinical campylobacteriosis." (PMID 25397604, 2014). "To further investigate the previous observation that IFNγ production is associated with protection from campylobacteriosis, we performed the first kinetic evaluation of T cell cytokine responses following human C. jejuni infection." (PMID 25397604, 2014). "One study reported that carvacrol ameliorates acute campylobacteriosis by reducing the serum levels of interferon-gamma (IFN-γ), TNF, monocyte chemoattractant protein-1 (MCP-1), and IL-614." (PMID 37550359, 2023).